NEAT1 (nuclear paraspeckle assembly transcript 1)
Diseases named in the same sentence as NEAT1 in open-access papers (continued):
Sharing a sentence is not in itself a finding about the gene and the disease.
ovarian carcinoma (continued). "LncRNA NEAT1 contributes to DDP resistance of ovarian cancer cells by regulating PARP1 expression via miR-770-5p." (PMID 34512721, 2021). "Studies have found that the expression of lncRNA NEAT1 is abnormally elevated in breast and ovarian cancer, and interference with the expression of lncRNA NEAT1 in vitro inhibits the proliferation of ovarian cancer cells." (PMID 32943985, 2020). "For example, LncRNA NEAT1 contributes to paclitaxel resistance of ovarian cancer cells by regulating ZEB1 expression via miR-194." (PMID 32296457, 2020). "LncRNA NEAT1 suppresses the inhibitory effect of miR-194 on ZEB1 to induce the resistance of ovarian cancer cells into PTX chemotherapy." (PMID 32664703, 2020). "In ovarian cancer, HuR stabilizes NEAT1 by inhibiting its binding with miR-124-3p, and upregulation of NEAT1 in ovarian cancer induces cancer cell proliferation and invasion." (PMID 32967226, 2020). "In ovarian cancer, NEAT1 is elevated and increases paclitaxel resistance of ovarian cancer via upregulating zinc finger E-box-binding homeobox 1 (ZEB1) expression by sponging miR-194." (PMID 33292252, 2020). "For instance, it was reported that lncRNA NEAT1 promotes ovarian cancer cell metastasis through regulation of miR-382-3p/ROCK1 axis." (PMID 33168781, 2020). "An example of an lncRNA that is well-known to be associated with cancer and whose stability has been found to be enhanced by HuR in ovarian cancer is NEAT1." (PMID 32340118, 2020). "Ji An, etc reported that lncRNA NEAT1 affected paclitaxel resistance in ovarian cancer by recruiting miR − 194 to target ZEB1 and then regulating P-gp and GST." (PMID 31391118, 2019). "This was also seen in ovarian cancer that NEAT1 suppressed apoptosis and increased S-phase cell population through regulating Bcl2 that is mediated by miR-34a-5p36." (PMID 30894512, 2019). "In ovarian cancer, NEAT1 contributed to paclitaxel resistance partly through upregulating ZEB1 expression by sponging miR-19441." (PMID 30894512, 2019). "Functional experiments demonstrated that knockdown of NEAT1 significantly prohibited ovarian cancer cell proliferation and invasion in vitro and restrained tumor growth in vivo." (PMID 30154460, 2018). "For example, miR-126 was demonstrated to be associated with clear cell human renal cell carcinoma, while miR-34a-5p was proven to have a critical impact on ovarian cancer (OC) cell lines via interacting with nuclear paraspeckle assembly transcript 1 (NEAT1)." (PMID 30597923, 2018). "A rescue functional assay confirmed that the LIN28B/NEAT1 axis contributed to oncogenic functions in ovarian cancer cells." (PMID 30154460, 2018). "Our results indicated that NEAT1 promoted ovarian cancer cell proliferation and metastasis partly in a LIN28B-regulated manner." (PMID 30154460, 2018). "The cell-wounding and Transwell assays also showed that NEAT1 knockdown partially attenuated the effects of LIN28B overexpression in ovarian cancer cells." (PMID 30154460, 2018). "For example, abnormal expression of lncRNA NEAT1 has a close relationship to the development of ovarian cancer occurrence, growth, invasion, and metastasis." (PMID 27911852, 2017). "For example, HuR RNA binding protein stabilizes the expression of Neat1 lncRNA in ovarian cancer tissues through direct binding." (PMID 29657295, 2017). "The nuclear paraspeckle assembly transcript 1 (NEAT1) is one of the most highly regulated lncRNAs in recent genomic datasets, however, its biological role and regulatory mechanism in ovarian cancer (OC) development and progression are poorly defined." (PMID 27075229, 2016). "Moreover, NEAT1 upregulation controls ZEB1 expression via miR-194 to help ovarian cancer cells resist paclitaxel through drug resistance." (PMID 40165339, 2025). "Additionally, DDSR1 supports BRCA1 recruitment during HR61, while targeting NEAT1 sensitices ovarian cancer cells to PARPi by regulating RAD5162." (PMID 41034557, 2025).
ovarian carcinoma (continued). "In addition to a direct role in ovarian cancer for NEAT1 by affecting homologous recombination, NEAT1 is also involved in phase-separated transcriptional condensates." (PMID 39831777, 2025). "Thus, NEAT1 overexpression leads to enhanced tumor growth and low apoptosis levels in Paclitaxel-resistant ovarian cancer cells." (PMID 41195272, 2025). "Moreover, NEAT1 indirectly modulated BCL2 expression in ovarian cancer cells by sponging miR-34a-5p58." (PMID 40730640, 2025). "For example, miR-124-3p is markedly decreased in ovarian cancer patients, and its tumor suppressive role might be due to its regulation of the lncRNA “Nuclear enriched abundant transcript 1” (NEAT1) expression." (PMID 39412616, 2025). "However, the expression and predictive roles of NEAT1 were assessed in ovarian cancer cell lines and a database of OC patients." (PMID 38356722, 2024). "NEAT1 expression is upregulated and let-7g is downregulated in ovarian cancer cells." (PMID 39337410, 2024). "NEAT1 knockdown sensitized ovarian cancer cells to Olaparib by targeting RAD51-HR." (PMID 38356722, 2024). "Therefore, an in-depth study of the mechanism of NEAT1 in tumor drug resistance is of great significance in developing new treatment strategies to improve the sensitivity of ovarian cancer patients to chemotherapy." (PMID 38356722, 2024). "Because NEAT1 knockdown decreased RAD51 levels and HR ability, we wondered whether knockout of NEAT1 sensitized ovarian cancer cells to Olaparib." (PMID 38356722, 2024). "The expressions of NEAT1 in most ovarian cancer cell lines were relatively high." (PMID 38356722, 2024). "Furthermore, we divided ovarian cancer patients into two groups (high and low) according to NEAT1 expression level using the ICGC database." (PMID 38356722, 2024). "The clinical samples from a large cohort can help evaluate the reliability of NEAT1 as a biomarker for ovarian cancer, which might be also employed to predict the prognosis of patients receiving chemotherapy, targeted therapy, and immunotherapy." (PMID 37986114, 2023). "Thus, the data presented herein clearly demonstrated that NEAT1 promoted in vivo angiogenesis in xenografted human ovarian cancer tissues." (PMID 37986114, 2023). "Since NEAT1 demonstrated significantly pro-proliferative effects in human ovarian cancer cells, we further examined the impacts of NEAT1 expression on apoptosis of SKOV-3 cells and A2780 cells, as well as their metastatic behaviors–the cellular traits of many malignant cells." (PMID 37986114, 2023). "We found that NEAT1 was highly expressed in human ovarian cancer cells." (PMID 37986114, 2023). "Furthermore, it is worth evaluating the efficacy of the targeted NEAT1 inhibition in combination with other therapies (including chemotherapy, targeted therapy, and immunotherapy) for treating ovarian cancer." (PMID 37986114, 2023). "Notably, NEAT1 has been reported to promote the proliferation and metastasis of ovarian cancer in multiple reports." (PMID 37986114, 2023). "In ovarian cancer cells, NEAT1 expression was upregulated, whereas let-7 g was decreased." (PMID 37310654, 2023). "Furthermore, we investigated the impacts of upregulated and downregulated NEAT1 expressions on proliferation of human ovarian cancer cells SKOV-3 and A2780." (PMID 37986114, 2023). "NEAT1 promotes angiogenesis and metastasis in human ovarian cancer." (PMID 37986114, 2023). "Our study identifies an NEAT1/miR-214-3p pathway in regulating angiogenesis and cancer metastasis, and suggests that the approaches targeting the molecules in this pathway can be utilized to treat ovarian cancer." (PMID 37986114, 2023). "In addition to employing CCK-8, transwell migration and invasion assays, our study utilized wound healing, cell colony formation ability, and in vivo xenograft animal models to further substantiate the role of NEAT1 in promoting ovarian cancer progression." (PMID 37986114, 2023).
ovarian carcinoma (continued). "NEAT1 upregulates the expression of angiogenesis-related molecules in human ovarian cancer cells." (PMID 37986114, 2023). "NEAT1 helps maintain cell viability and the trait of metastasis in human ovarian cancer cells." (PMID 37986114, 2023). "NEAT1 was highly expressed in ovarian cancer tissues of patients and cell lines." (PMID 37986114, 2023). "Therefore, it is plausible that rather than a single pathway, a complexed network of multiple pathways is involved in executing the oncogenic function of NEAT1 in ovarian cancer cells." (PMID 37986114, 2023). "In this study, we evaluated the expression level of NEAT1 in clinically resected samples from patients with ovarian cancer and two human ovarian cancer cell lines, and identified that a higher level of NEAT1 was associated with the malignancies of ovarian cancer cells." (PMID 37986114, 2023). "NEAT1 can also regulate glucose metabolism to promote ovarian cancer’s progression." (PMID 36011001, 2022). "Specifically, HuR and LIN28B can promote ovarian cancer progression via stabilizing NEAT1." (PMID 36011001, 2022). "Moreover, the expression level of NEAT1 is higher in ovarian cancer cell lines including ES2, A2780, HO8910, and SKOV3 than the normal ovarian epithelial cell line IOSE80." (PMID 36011001, 2022). "In the exosomes extracted from patients with ovarian cancer, NEAT1 expression levels are upregulated and may contribute to cisplatin resistance." (PMID 36011001, 2022). "Recently, LncRNA NEAT1 is also found to play a part in cisplatin resistance of ovarian cancer." (PMID 34512721, 2021). "Cumulatively, the findings demonstrated that NEAT1 could promote malignant phenotypes of ovarian cancer cells by regulating the let-7 g/MEST/ATGL signaling axis." (PMID 34416900, 2021). "Furthermore, silencing of NEAT1 has been found to markedly inhibit the invasion of ovarian cancer cells in vitro and attenuate tumor growth in vivo." (PMID 34416900, 2021). "LncRNA NEAT1 regulates miR-770-5p/PARP1 signaling to induce cisplatin resistance in ovarian cancer." (PMID 34660304, 2021). "Finally, it has been shown that nuclear enriched abundant transcript 1 (NEAT1) was overexpressed in ovarian cancer tissues and cell lines." (PMID 34204094, 2021). "In conclusion, the current study provides evidence indicating that NEAT1 can potentially promote the growth, migration, and invasion of ovarian cancer cells in vitro as well as tumor growth in vivo by competitively binding to let-7 g, promoting MEST expression and inhibiting ATGL expression." (PMID 34416900, 2021). "Knockdown of NEAT1 suppresses cisplatin resistance of ovarian cancer cells in vitro and in vivo." (PMID 34512721, 2021). "Additionally, NEAT1 knockdown has been reported to suppress ovarian cancer cell proliferation, colony formation, migration, and invasion while stimulating cell apoptosis." (PMID 34416900, 2021). "Furthermore, they showed that overexpression of HuR in an ovarian carcinoma cell line (OVCAR-3) resulted in significantly increased levels of NEAT1, whereas HuR knockdown led to a reduction of NEAT1." (PMID 32340118, 2020). "LncRNA NEAT1 was also found to mediate PTX resistance in ovarian cancer cells." (PMID 32664703, 2020). "To examine whether NEAT1 could bind to other RBPs in ovarian cancer cells, we performed a bioinformatics analysis, RNA pulldown assay, and RIP assay, which revealed that NEAT1 could combine with LIN28B." (PMID 30154460, 2018). "After knocking down NEAT1, the malignant behaviors of ovarian cancer cells were restrained." (PMID 30154460, 2018). "Rescue assays confirmed the function of the LIN28B/NEAT1 axis in ovarian cancer cells." (PMID 30154460, 2018). "NEAT1 expression could predict response to chemotherapy for ovarian cancer." (PMID 38356722, 2024). "Thus, NEAT1 is a promising biomarker for predicting the prognosis of patients with ovarian cancer." (PMID 37986114, 2023).
ovarian carcinoma (continued). "In addition, more work on validating the therapeutic effects of in vivo knockdown of NEAT1, as well as the delivery of miR-214-3p mimics, in xenograft animal models is warranted to substantiate the potential of targeting the NEAT1/miR-214-3p axis to treat patients with ovarian cancer." (PMID 37986114, 2023). "Therefore, NEAT1 promoted cell proliferation in human ovarian cancer cells." (PMID 37986114, 2023). "Furthermore, NEAT1 could stimulate the growth, migration, and invasion of ovarian cancer cells by inhibiting the expression of let-7 g." (PMID 34416900, 2021). "However, whether other miRNAs known to interact with NEAT1 in ovarian cancer can also target the MEST or ATGL genes requires further comprehensive investigations." (PMID 34416900, 2021). "Therefore, NEAT1 can be regarded as an important molecular target and biomarker for ovarian cancer." (PMID 34416900, 2021). "Therefore, targeting the NEAT1-let-7 g axis might be an effective strategy for the treatment of ovarian cancer." (PMID 34416900, 2021). "A prognostic signature with eleven lncRNAs, including NEAT1, HOTAIR, MALAT1, ANRIL, CCAT2, ZFAS1, UCA1 have been shown to predict poor patient survival and outcome in ovarian cancer patients." (PMID 39912983, 2025). "NEAT1 acts as a ceRNA in oncogenic cells, targeting miR-101-3p and enhancing the expression of ZEB1, resulting in the proliferation of ovarian cancer cells, tumour growth and apoptosis of CD8+ cells via miR-101-3p/ZEB1/PD-L1 pathway." (PMID 40176927, 2024). "It was recently shown that EVO decreases the expression of NEAT1 and CDK19, but increases miR-152 expression in ovarian cancer cells." (PMID 37046995, 2023). "It has been invested that high expression of NEAT1 can inhibit miR‐4500 and stimulate basic leucine zipper and W2 domain‐containing protein 1 (BZW1) in ovarian cancer cells." (PMID 37310654, 2023). "Next, we evaluated the expression levels of NEAT1 and its putative sponging target miR-214-3p in human ovarian surface epithelial cell line IOSE80 and two common human ovarian cancer cell lines SKOV-3 and A2780." (PMID 37986114, 2023). "We found that SKOV-3 and A2780 cells had over 2.5-fold expression of NEAT1 than IOSE80 cells, while IOSE80 cells showed a markedly higher expression level of miR-214-3p than the two ovarian cancer cell lines." (PMID 37986114, 2023). "For instance, the knockdown of NEAT1 has been shown to upregulate miR-4500 and downregulate BZW1, subsequently inhibiting the glycolysis of ovarian cancer." (PMID 36011001, 2022). "NEAT1 can upregulate the expression of TJP3, MEST, and ROCK1 in ovarian cancer cell lines, subsequently promoting the progression of ovarian cancer." (PMID 36011001, 2022). "LncRNA NEAT1 overexpression sponged miR-770-5p and inhibited the expression of PARP1, leading to cisplatin resistance in ovarian cancer." (PMID 36105363, 2022). "LncRNA NEAT1 depletion abrogated the cisplatin resistance via modulation of miR-770-5p and PARP1 in ovarian cancer." (PMID 36105363, 2022). "Additional studies on the effects of NEAT1, MALAT1 and MEG3 aberrant expression in CCs should bring critical insights into their function during oocyte maturation and in ovarian carcinoma." (PMID 29396444, 2018). "NEAT1 knockdown in ovarian cancer cells resulted in a decrease in Snail1, TGF-β1, MMP-2 and MMP-9 and so presumably promotes EMT in ovarian cancer." (PMID 28430163, 2017). "In ovarian cancer tissues and cell lines resistant to paclitaxel (PTX), NEAT1 also lowers miR-194." (PMID 39337410, 2024). "In addition, NEAT1 can target miR-152-3p to up-regulate the expression of CDK19 and promote the cell viability, cycle and apoptosis of ovarian cancer cells, which can be reversed by evodiamine." (PMID 38970092, 2024). "Ovarian cancer (OC) cells HeyA8 and SKOV3 were silenced by transfecting NEAT1 ASO." (PMID 38356722, 2024).
ovarian carcinoma (continued). "In another study, the knockdown of NEAT1 improved cisplatin response by increasing miR-770-5p and decreasing PARP1, demonstrating a novel treatment target for enhancing the efficacy of cisplatin in ovarian cancer cells." (PMID 38356722, 2024). "The expressions of NEAT1 and RAD51 in ovarian cancer cells were negatively correlated." (PMID 38356722, 2024). "Multiple putative miRNA targets of NEAT1 and the downstream proteins have been proposed to contribute to the oncogenic roles of NEAT1 in ovarian cancer, such as the NEAT1/miR-1312/TJP3, NEAT1/miR-506, NEAT1/let-7 g/MEST/ATGL, NEAT1/miR‐382‐3p/ROCK1, and NEAT1/miR-365/FGF9 axes." (PMID 37986114, 2023). "It has been demonstrated that NEAT1 and FGF9 are overexpressed in ovarian cancer cells." (PMID 37310654, 2023). "Clinical data showed that highly-expressed NEAT1 is closely correlated with a shorter survival rate, a poor differentiation degree, larger tumors, an advanced FIGO stage, and significant peritoneal metastasis in patients with ovarian cancer." (PMID 36011001, 2022). "Yet another study also established that the expression of NEAT1 was markedly heightened in ovarian cancer tissues in comparison to the corresponding adjacent non-neoplastic tissues." (PMID 34416900, 2021). "More importantly, the same authors reported that the expression of NEAT1_2, but not total NEAT1, predicted progression-free survival of ovarian cancer treated with platinum-based chemotherapy." (PMID 31992741, 2020). "Moreover, MALAT1, NEAT1, GAS5, H19 and XIST have been experimentally validated to be ovarian cancer-related lncRNAs, which were identified as hubs that connect 26, 15, 22, 20 and 9 modules in OV dataset, respectively." (PMID 30732558, 2019). "However, the connection between NEAT1 and miR-214-3p, and the roles of NEAT1 in angiogenesis of ovarian cancer, have not been intensively elucidated so far." (PMID 37986114, 2023). "The expression level of NEAT1 appeared to be positively correlated with the viability of SKOV-3 and A2780 cells, which suggests that NEAT1 might be a possible biomarker in predicting overall and disease-free survival outcomes of patients with ovarian cancer." (PMID 37986114, 2023). "The two siRNAs resulted in the nearly identical arrest of ovarian cancer cell proliferation and migration, which suggested that targeting only NEAT1-2, which was recognized as the predominant isoform for the function of NEAT1 in the paraspeckle, did not have a stronger oncogenic effect." (PMID 30154460, 2018).